ARRB1 (arrestin beta 1)
Description:
Functions in regulating agonist-mediated G protein-coupled receptor (GPCR) signaling by mediating both receptor desensitization and resensitization processes. During homologous desensitization, beta-arrestins bind to the GPCR-phosphorylated receptor and sterically preclude its coupling to the cognate G protein; the binding appears to require additional receptor determinants exposed only in the active receptor conformation. The beta-arrestins target many receptors for internalization by acting as endocytic adapters (CLASPs, clathrin-associated sorting proteins) and recruiting the GPRCs to the adapter protein 2 complex 2 (AP-2) in clathrin-coated pits (CCPs). However, the extent of beta-arrestin involvement appears to vary significantly depending on the receptor, agonist and cell type. Internalized arrestin-receptor complexes traffic to intracellular endosomes, where they remain uncoupled from G proteins. Two different modes of arrestin-mediated internalization occur. Class A receptors, like ADRB2, OPRM1, ENDRA, D1AR and ADRA1B dissociate from beta-arrestin at or near the plasma membrane and undergo rapid recycling. Class B receptors, like AVPR2, AGTR1, NTSR1, TRHR and TACR1 internalize as a complex with arrestin and traffic with it to endosomal vesicles, presumably as desensitized receptors, for extended periods of time. Receptor resensitization then requires that receptor-bound arrestin is removed so that the receptor can be dephosphorylated and returned to the plasma membrane. Involved in internalization of P2RY4 and UTP-stimulated internalization of P2RY2. Involved in phosphorylation-dependent internalization of OPRD1 ands subsequent recycling. Involved in the degradation of cAMP by recruiting cAMP phosphodiesterases to ligand-activated receptors. Beta-arrestins function as multivalent adapter proteins that can switch the GPCR from a G protein signaling mode that transmits short-lived signals from the plasma membrane via small molecule second messengers and ion channels to a beta-arrestin signaling mode that transmits a distinct set of signals that are initiated as the receptor internalizes and transits the intracellular compartment. Acts as a signaling scaffold for MAPK pathways such as MAPK1/3 (ERK1/2). ERK1/2 activated by the beta-arrestin scaffold is largely excluded from the nucleus and confined to cytoplasmic locations such as endocytic vesicles, also called beta-arrestin signalosomes. Recruits c-Src/SRC to ADRB2 resulting in ERK activation. GPCRs for which the beta-arrestin-mediated signaling relies on both ARRB1 and ARRB2 (codependent regulation) include ADRB2, F2RL1 and PTH1R. For some GPCRs the beta-arrestin-mediated signaling relies on either ARRB1 or ARRB2 and is inhibited by the other respective beta-arrestin form (reciprocal regulation). Inhibits ERK1/2 signaling in AGTR1- and AVPR2-mediated activation (reciprocal regulation). Is required for SP-stimulated endocytosis of NK1R and recruits c-Src/SRC to internalized NK1R resulting in ERK1/2 activation, which is required for the antiapoptotic effects of SP. Is involved in proteinase-activated F2RL1-mediated ERK activity. Acts as a signaling scaffold for the AKT1 pathway. Is involved in alpha-thrombin-stimulated AKT1 signaling. Is involved in IGF1-stimulated AKT1 signaling leading to increased protection from apoptosis. Involved in activation of the p38 MAPK signaling pathway and in actin bundle formation. Involved in F2RL1-mediated cytoskeletal rearrangement and chemotaxis. Involved in AGTR1-mediated stress fiber formation by acting together with GNAQ to activate RHOA. Appears to function as signaling scaffold involved in regulation of MIP-1-beta-stimulated CCR5-dependent chemotaxis. Involved in attenuation of NF-kappa-B-dependent transcription in response to GPCR or cytokine stimulation by interacting with and stabilizing CHUK. May serve as nuclear messenger for GPCRs. Involved in OPRD1-stimulated transcriptional regulation by translocating to CDKN1B and FOS promoter regions and recruiting EP300 resulting in acetylation of histone H4. Involved in regulation of LEF1 transcriptional activity via interaction with DVL1 and/or DVL2 Also involved in regulation of receptors other than GPCRs. Involved in Toll-like receptor and IL-1 receptor signaling through the interaction with TRAF6 which prevents TRAF6 autoubiquitination and oligomerization required for activation of NF-kappa-B and JUN. Binds phosphoinositides. Binds inositolhexakisphosphate (InsP6) (By similarity). Involved in IL8-mediated granule release in neutrophils. Required for atypical chemokine receptor ACKR2-induced RAC1-LIMK1-PAK1-dependent phosphorylation of cofilin (CFL1) and for the up-regulation of ACKR2 from endosomal compartment to cell membrane, increasing its efficiency in chemokine uptake and degradation. Involved in the internalization of the atypical chemokine receptor ACKR3. Involved in smoothened (SMO) localization to primary cilium (By similarity). Negatively regulates the NOTCH signaling pathway by mediating the ubiquitination and degradation of NOTCH1 by ITCH. Participates in the recruitment of the ubiquitin-protein ligase to the receptor. Involved in some MRGPRE-mediated signaling required to improve glucose tolerance: promotes phosphorylation of ALDOA downstream of MRGPRE activation, increasing glycolysis and leading to GLP-1 secretion.
Synonyms: ARR1; ARB1
Tractability: Small molecule: a structure with a bound ligand is known. Antibody: its Gene Ontology location is reachable by antibodies, with high confidence; UniProt places it where antibodies can reach, with medium confidence. PROTAC: UniProt records ubiquitination sites on it; ubiquitination databases record sites on it; its protein half-life has been measured; a small molecule that binds it is known.
Gene: Protein-coding gene on chromosome 11 (75,260,122 to 75,351,791, reverse strand). Ensembl gene ENSG00000137486.
Subcellular location: Cytoplasm; Nucleus; Cell membrane; Membrane, clathrin-coated pit; Cell projection, pseudopodium; Cytoplasmic vesicle
Subcellular location (Human Protein Atlas): Nucleoplasm
Pathways (Reactome):
Disease: Paradoxical activation of RAF signaling by kinase inactive BRAF; Signaling by BRAF and RAF1 fusions; Signaling by RAF1 mutants; Signaling by high-kinase activity BRAF mutants; Signaling by moderate kinase activity BRAF mutants; Signaling downstream of RAS mutants
Signal Transduction: Activated NOTCH1 Transmits Signal to the Nucleus; Activation of SMO; G alpha (s) signalling events; MAP2K and MAPK activation; TGFBR3 regulates TGF-beta signaling
Vesicle-mediated transport: Cargo recognition for clathrin-mediated endocytosis; Clathrin-mediated endocytosis; Golgi Associated Vesicle Biogenesis; Lysosome Vesicle Biogenesis
Hemostasis: Thrombin signalling through proteinase activated receptors (PARs)
Metabolism of proteins: Ub-specific processing proteases
Gene Ontology:
Molecular function: angiotensin receptor binding; arrestin family protein binding; G protein-coupled receptor binding; GTPase activator activity; histone acetyltransferase activity; insulin-like growth factor receptor binding; molecular adaptor activity; protein binding; protein-macromolecule adaptor activity; transcription coactivator activity; ubiquitin protein ligase binding; enzyme inhibitor activity; cysteine-type endopeptidase inhibitor activity; enzyme binding; mitogen-activated protein kinase kinase binding
Biological process: cell surface receptor signaling pathway; desensitization of G protein-coupled receptor signaling pathway; G protein-coupled receptor internalization; intracellular glucose homeostasis; intraciliary retrograde transport; negative regulation of canonical NF-kappaB signal transduction; negative regulation of interleukin-6 production; negative regulation of interleukin-8 production; negative regulation of Notch signaling pathway; negative regulation of protein localization to ciliary membrane; positive regulation of ERK1 and ERK2 cascade; positive regulation of protein phosphorylation; positive regulation of receptor internalization; positive regulation of Rho protein signal transduction; positive regulation of transcription by RNA polymerase II; proteasome-mediated ubiquitin-dependent protein catabolic process; protein ubiquitination; regulation of transcription by RNA polymerase II; stress fiber assembly; ubiquitin-dependent protein catabolic process; positive regulation of smoothened signaling pathway; protein localization to non-motile cilium; sensory perception; positive regulation of insulin secretion involved in cellular response to glucose stimulus; positive regulation of intracellular signal transduction; and 2 more
Cellular component: chromatin; cytoplasm; cytoplasmic vesicle; nucleoplasm; nucleus; cytoplasmic vesicle membrane; cytosol; endocytic vesicle membrane; Golgi membrane; lysosomal membrane; plasma membrane; cilium; clathrin-coated pit; pseudopodium
Genetic constraint (gnomAD): Loss-of-function variants: 21 observed, 49.51 expected, observed/expected ratio (o/e) 0.42, 90% interval 0.3 to 0.61. The upper end of that interval is the gene's LOEUF score, 0.61, which puts it in group 2 of 6, group 1 being the genes least tolerant of losing a copy. Missense variants: 424 observed, 548.96 expected, observed/expected ratio (o/e) 0.77, 90% interval 0.71 to 0.84. Synonymous variants: 210 observed, 217.51 expected, observed/expected ratio (o/e) 0.97, 90% interval 0.86 to 1.08.
Homologues: Orthologues: chimpanzee ARRB1 (100% identical), pig ARRB1 (99% identical), mouse Arrb1 (97% identical), guinea pig ARRB1 (97% identical), dog ARRB1 (96% identical), rat Arrb1 (96% identical), tropical clawed frog arrb1 (93% identical), zebrafish arrb1 (90% identical), rabbit ARRB1 (89% identical), macaque ARRB1 (89% identical), Drosophila melanogaster krz (62% identical), Caenorhabditis elegans arr-1 (55% identical). Paralogues in human: ARRB2 (76% identical), ARR3 (56% identical), SAG (55% identical).
Diseases named in the same sentence as ARRB1 in open-access papers:
ARRB1 is named in the same sentence as 100 diseases in open-access papers, as found by Europe PMC text mining. Sharing a sentence is not in itself a finding about the gene and the disease. The quoted sentences say what the papers report.
lung cancer (10 papers, 2013 to 2025). A malignant neoplasm involving the lung. "A potential role of ARRB1 in maintaining SC characteristics has also been demonstrated in nonsmall cell lung cancer cells." (PMID 33920080, 2021). "In a more recent study, ARRB1 was found to promote the migratory ability of lung cancer migration." (PMID 24260584, 2013). "In addition, ARRB1 was a potential biomarker in lung cancer to distinguish LUAD from LUSC." (PMID 37477536, 2023). "ARRB1 expression is increased in tumor tissues of lung cancer including LUSC, and overexpression ARRB1 promotes cell proliferation." (PMID 40425760, 2025). "Increased abundance of ARRB1, as well as FBXO11, LYZ, RPS6KB1, and SYNGR2 have comparable oncogenic effects in hepatocellular carcinoma, and MGST1 and RPS6KB1 have noted oncogenic roles in various lung cancers." (PMID 40186098, 2025). "Interestingly, we observed that a positive correlation exists between ARRB1 and most MHC molecules in LUSC, while the opposite is true in LUAD, suggesting that the immunomodulatory effects of ARRB1 differ according to the lung cancer type." (PMID 36213111, 2022).
breast carcinoma (8 papers, 2013 to 2023). "The expression of AMOTL1 and IFRD1 was linked to an increased risk of breast cancer, whereas ARRB1 was associated with a protective effect." (PMID 37644433, 2023). "A recent study describing a role for ARRB1 in HIF1A-dependent VEGFA expression in breast cancer cells supports our findings." (PMID 24837709, 2014). "In contrast, overexpression of β-arrestin-1 (ARRB1) reduced the migratory propensity of breast cancer cells lines, whereas silencing increased migration." (PMID 24260584, 2013). "Moreover, the levels of ARRB1-Δexon 13 in HGG and RecG tissues and breast cancer tissues were analyzed, and we found that this alternative isoform, ARRB1-Δexon 13, was upregulated in cancerous tissues compared with normal tissues and LGG." (PMID 37988165, 2023). "In addition, ARRB1 expression was significantly higher in normal tissue than in breast cancer tissue, as well as in higher-stage tumors relative to lower-stage ones." (PMID 36213111, 2022). "In contrast, a different study reported that ARRB1 mediated the metastatic growth of breast cancer cells by promoting VEGF expression, suggesting that ARRB1 may play dual and opposing roles in breast cancer." (PMID 36213111, 2022). "ARRB1 high expression inhibited TNBC cell proliferation and migration and is negatively correlated with breast cancer histological grade and favorably associated with TNBC patient survival, suggesting that ARRB1 has a tumor-suppressive function in breast cancer." (PMID 36476410, 2022). "PCR and subsequent agarose gel electrophoresis (AGE) results showed that AEP/tDDX3X-C enhanced the ES of PRDM2 exon 2, ARRB1 exon 13, and NCOR2 exon 21 in both glioma and breast cancer cells." (PMID 37988165, 2023). "On the other hand, TCF7L2, ARRB1, DLL1, FZD7, HES1, and JAG1 transcript levels were significantly lower in breast cancer tissues than in normal samples (p < 0.0009, p = 0.0131, p = < 0.0001, p = < 0.0001, p = 0.0138, and p < 0.0001, respectively)." (PMID 36476410, 2022). "Certain studies have confirmed the role of ARRB1 in tumorigenesis, including nicotine-induced carcinogenesis in the lungs by nuclear translocation of ARRB1 and LPA-induced breast cancer through ARRB1-mediated cell migration and invasion." (PMID 34380537, 2021). "MiR-374a-5p was able to target arrestin beta 1 (ARRB1) that was downregulated in TNBC patients and the ARRB1 expression was inversely correlated with the histological grade of breast cancer and correlated with the survival of TNBC patients." (PMID 31766744, 2019). "One such study showed ARRB1 to co-localise and physically interact with hypoxia-inducible factor 1A (HIF1A) in the nucleus of breast cancer cells to potentiate HIF1-dependent transcription, thereby mediating metastatic growth of breast cancer cells." (PMID 24837709, 2014). "Consistent with the literature, which reported promotion of tumor proliferation in gastric cancer, WT ARRB1 could partially rescue the AEP KD phenomenon in GBM and breast cancer." (PMID 37988165, 2023).
prostate carcinoma (8 papers, 2014 to 2024). A carcinoma that arises from epithelial cells of the prostate gland. "Herein, we present the first whole-genome description of the transcriptional networks and associated pathways controlled by an endocytic adaptor, ARRB1, in prostate cancer cells." (PMID 24837709, 2014). "ARRB1 has been demonstrated to be a potential tumor promoter in prostate cancer and is important for metabolic alterations in prostate cancer." (PMID 35711827, 2022). "Having identified the genomic landscape of ARRB1 in prostate cancer cell lines, we validated our findings in vivo by examining its binding to chromatin in human prostate tissue." (PMID 24837709, 2014). "Altogether, these results demonstrate a role for ARRB1 as a regulator of hypoxia-mediated HIF1A transcriptional activity in prostate cancer cells." (PMID 24837709, 2014). "It implicates ARRB1 as a potential tumour promoter in prostate cancer and highlights the importance of metabolic alterations in prostate cancer." (PMID 24837709, 2014). "To determine the effect of ARRB1 on gene expression in prostate cancer cells, we performed genome-wide expression profiling using Illumina bead arrays." (PMID 24837709, 2014). "We report a nuclear physical interaction between ARRB1 and HIF1A in prostate cancer cells and show that it occurs at the chromatin level, where recruitment of ARRB1 to HREs at functional promoters of HIF1A targets upon hypoxia is HIF1A dependent." (PMID 24837709, 2014). "Similarly, ARRB1-mediated inhibition of FOXO3a was reported to contribute to the growth of prostate cancer cells both in vitro and in vivo, an effect that was likely exerted via the promotion of cell proliferation and EMT." (PMID 36213111, 2022). "Interestingly, the authors observed an increase in TCA cycle metabolite level in prostate cancer cells with nuclear localization of ARRB1." (PMID 33920080, 2021). "However, the adaptor protein beta-arrestin 1 (ARRB1) was a possible candidate, since ARRB1 was capable of inducing fumarate level in prostate cancer cells." (PMID 32640711, 2020). "Thus, our metabolomic analysis indicates that overexpression of nuclear ARRB1 in prostate cancer cells promotes profound metabolic changes that would fuel the increased energy demands of growth and proliferation of cancer cells." (PMID 24837709, 2014). "As nuclear ARRB1 levels are increased in prostate cancer, we hypothesised that gene expression might be dysregulated in a similar way in nucARRB1 and prostate cancer tissue." (PMID 24837709, 2014). "In addition, we found ARRB1 to be in the top 1% overexpressed genes in prostate carcinoma compared to normal tissue in a recent clinical gene expression study." (PMID 24837709, 2014). "Our study implicates ARRB1 as a regulator of metabolism in prostate cancer cells." (PMID 24837709, 2014). "We show here that high levels of nuclear ARRB1 in prostate cancer cells result in downregulation of FH and SDHA expression, although this effect is likely to be an indirect consequence as our genomics analysis did not identify any ARRB1-binding sites in the promoter regions of these two genes." (PMID 24837709, 2014). "Thus, ARRB1 acts a co-regulator of HIF1A activity in prostate cancer cells." (PMID 24837709, 2014). "Our findings indicate that the regulation of tumour cell metabolism by ARRB1 could provide an important area for cancer diagnosis and that preventing its nuclear import could be exploited as a therapeutic tool in limiting prostate cancer progression and metastasis." (PMID 24837709, 2014). "Further, the results demonstrated that Tmprss2 was significantly involved in the “prostate cancer” KEGG pathway, as well as in the “import into cell” term with Per2, Atp1a1, and Arrb1 (GO:0098657, FDR = 3.39 × 10−5)." (PMID 34834564, 2021).
prostate carcinoma (continued). "We identify a nuclear interaction between ARRB1 and HIF1A in prostate cancer cells and demonstrate that ARRB1 is recruited to promoter regions of metabolic genes in a HIF1A-dependent manner where it contributes to metabolic genes expression as a co-regulator of HIF1A transcriptional activity." (PMID 24837709, 2014). "Despite this, there have been no studies on the involvement of ARRB1 in prostate cancer." (PMID 24837709, 2014).
hepatocellular carcinoma (6 papers, 2021 to 2025). A malignant tumor that arises from hepatocytes. "In a different study, meanwhile, the authors noted that ARRB1 influenced the metastasis of hepatocellular carcinoma via extracellular signal-regulated kinase-mediated EMT." (PMID 36213111, 2022). "Our previous study demonstrated that ARRB1 was involved in chronic liver diseases, such as liver cirrhosis and hepatocellular carcinoma." (PMID 34455423, 2021). "Recent data has suggested that ARRB1 promotes hepatocellular carcinoma cell invasion and metastasis through p-ERK1/2-mediated EMT, and thus the suppression of p-ERK1/2 may offer potential therapeutic targets for hepatocellular carcinoma therapy." (PMID 34405010, 2021).